EGR1 (early growth response 1)
Diseases named in the same sentence as EGR1 in open-access papers (continued):
Sharing a sentence is not in itself a finding about the gene and the disease.
infection (continued). "Notably, expression of the EGR1 and FOS transcription factors, which are known to be regulated by MAPK signaling pathways, was reduced in T3SS1+ΔvopQ-infected cells compared to T3SS1+-infected cells and highly elevated by T3SS1+ΔvopS infection (Data Set S1)." (PMID 33563785, 2021). "Interestingly, C. rodentium-challenged mPG-1-treated mice did not display upregulated EGR1 expression, possibly due to mPG-1 clearing the infection by this time point, resulting in reduced apoptosis and less need for cell proliferative factors." (PMID 34502403, 2021). "In addition, EGR-1 protein was no longer detectable in cell extracts from infected cells at later times during infection." (PMID 29561772, 2018). "Next, we investigated the effect of EGR1 and c-FOS on the phagocytosis, the RNA levels of phagocytic receptors mannose receptor (MR) and scavenger receptor (SR) were determined in THP-1 macrophage cells after silencing EGR1 and c-FOS for 24 h, and followed by PA infection for 1 h." (PMID 29487594, 2018). "Hence, these observations indicated that Egr-1 and CBP could be cooperatively acting during KSHV de novo infection." (PMID 29207655, 2017). "In addition, infection by UV-inactivated virus, which allows entry but no viral transcription, did not induce Egr-1." (PMID 25264522, 2013). "Western blot analyses showed that Egr-1 was absent in uninfected cells; however, the protein was detected 24-72 hours post treatment, and the response was directly proportional to the titer of the virus used for infection." (PMID 21619646, 2011). "However, Egr1 transcript accumulation was not significantly reduced when host cell membranes were penetrated by the injectisome but delivery of subsequent effectors was prevented by SptP-GFP induction at 5 min post infection." (PMID 41188240, 2025). "As EGR1 is known to act as a DNA-binding transcription factor, we hypothesized that EGR1 suppresses inflammation through transcriptional regulation and so time-resolved transcriptomic analysis of WT Salmonella-infected EGR1KO or EGR1WT macrophages from 15 to 240 min post infection was performed." (PMID 41188240, 2025). "Therefore, determining the role of EGR1 and UPR may play a significant role in the development of a novel therapeutic target resulting in decreased neuronal death and the subsequent neuronal sequelae that result from infection." (PMID 26792742, 2016). "While not significantly upregulated following infection, transcription of ATF3, CXCL3, CXCL8, and PTGS2 was at least partially dependent on EGR1." (PMID 35746681, 2022). "For example, although the levels of EGR1 and c-FOS were markedly increased shortly after infection, 10 h after infection these proteins were not detectable in lysates of Salmonella infected cells." (PMID 24098123, 2013). "In the absence of infection, silencing of c-KIT expression by siRNA did not induce any significant change in the expression levels of EGR1 or the tested cytokines and transcription factors." (PMID 24206648, 2013). "Therefore, we generated EGR1 knockout (EGR1KO) macrophages using CRISPR-Cas9 and confirmed the absence of EGR1 protein 120 min after infection with WT Salmonella." (PMID 41188240, 2025). "Given the regulatory relationship that exists between EGR1 and HPSE, we suspect that in the absence of HPSE expression, EGR1 upregulation upon infection remains unchecked and that this uncontrolled EGR1 level results in hyperactivation of the type I IFN system." (PMID 33621216, 2021). "Since PCIF1 was not significantly changed at day 1 post-infection, suggesting that PCIF1 may not be the only factor affecting FOS and EGR1 expressions during HIV infection." (PMID 34545078, 2021). "However, enhanced cellular Egr-1 and viral RTA expression during early stages of primary infection is not sufficient to trigger a lytic infection." (PMID 22428032, 2012).
cardiovascular disease (15 papers, 2013 to 2025). "Catalytic and non-catalytic nucleic acid approaches, such as DNAzymes, miRNAs, and ODNs decoys, have been used to investigate the primary regulatory role of Egr-1 in cardiovascular diseases, using animal models and Egr-1-deficient mice." (PMID 37057102, 2023). "It was noted that ED5 inhibited the EGR1 level and regulated the cardiovascular diseases caused by intimal thickening after permanent carotid artery ligation in rats." (PMID 37057102, 2023). "Egr-1 is an immediate-early gene and a zinc finger transcriptional protein that has been associated with several cardiovascular diseases." (PMID 32879888, 2020). "Does Egr-1 undergo post-translational modification(s), dynamic or otherwise, in the context of a specific cardiovascular disease?" (PMID 39619154, 2024). "The breadth of dependent genes and scope of proliferative, migratory, immune and inflammatory conditions that EGR1 controls suggest this factor represents a fertile therapeutic target for drug development for many types of cardiovascular disease." (PMID 39619154, 2024). "How can ERK-dependent Egr-1 promoter activation be studied separately from ERK-dependent Egr-1 phosphorylation in the context of cardiovascular disease when Egr-1 is expressed so rapidly?" (PMID 39619154, 2024). "This article briefly reviews emerging evidence further implicating Egr-1 in the pathogenesis of cardiovascular disease." (PMID 39619154, 2024). "The transcription factor, early growth response-1 (Egr-1) is the product of a prototypic immediate-early gene that plays an integral role in the pathogenesis of multiple cardiovascular diseases." (PMID 39619154, 2024). "Additionally, several Dox_H3K27ac-upregulated genes including Egr-1, Adam17, Dusp6, Ddit4 and Angptl4 might potentially contribute to Dox-induced cardiotoxicity, since they have been proved to be associated with the progression of cardiovascular disease." (PMID 39014511, 2024). "Earlier studies have shown that numerous cardiovascular disorders are related to the regulation of EGR1 by miRNAs." (PMID 37057102, 2023). "The primary regulatory role played by the Egr-1-targeting DNAzymes, microRNAs, and oligonucleotide decoy strategies in cardiovascular diseases were identified to provide a reference to identify novel therapeutic targets for cardiovascular diseases." (PMID 37057102, 2023). "EGR1, a transcription factor involved in multiple cardiovascular diseases, vascular dysfunction, and inflammatory disorders, is enriched in the coronary ECs in both injured human and mouse hearts." (PMID 36082978, 2023). "Egr-1 is also involved in preserving heart homeostasis and assists in the development of cardiovascular disorders." (PMID 37057102, 2023). "Notably, EGR1 is a direct downstream target of the ERK, and the MEK/ERK/EGR1 axis has been implicated in cardiovascular disease." (PMID 40292315, 2025). "EGR1's interaction with C/EBPβ controls transcription of the human low-density lipoprotein (LDL) receptor gene, which is linked with hypercholesterolemia and cardiovascular disease." (PMID 39619154, 2024). "Early growth response transcription factor (EGR1) has been subject to reports linked to its negative role in cardiovascular disease progression, profibrotic response, and physiologic and pathological connective tissue remodeling." (PMID 39012095, 2024). "In conclusion, Egr-1 can be regarded as a potential therapeutic target for cardiovascular diseases." (PMID 37057102, 2023). "Egr-1 is a redox-sensitive gene and is involved in the pathophysiology of cardiovascular diseases." (PMID 37057102, 2023). "Studies have demonstrated that Egr-1 is regulated by miRNAs in several cardiovascular diseases." (PMID 32879888, 2020).
cardiovascular disease (continued). "Additionally, researchers have used catalytic and non-catalytic nucleic acid methods such as DNAzymes, microRNAs, and oligonucleotide decoys in animal models in conjunction with Egr-1-deficient mice to obtain novel insights into the regulatory role played by Egr-1 in cardiovascular diseases." (PMID 37057102, 2023). "Therefore, it is important to understand the Egr-1 regulation mechanism, as it could help in the future treatment of cardiovascular diseases." (PMID 37057102, 2023). "EGR1 has an important role in the inflammatory response, it is involved in the proliferation, survival and differentiation of lymphocytes B and it has also been reported as an important hub protein deregulated in inflammatory and cardiovascular disorders as well as responsive to multiple stimuli." (PMID 29932449, 2018). "Additionally, many articles have described Egr-1 function without clarifying direct molecular mechanisms in a specific cardiovascular disease." (PMID 39619154, 2024).
psychiatric disorder (13 papers, 2015 to 2025). A disorder characterized by behavioral and/or psychological abnormalities, often accompanied by physical symptoms. "Finally, the results from our study together with the current literature suggest that the EGR1 pathway has a key role in mediating the environmental influences and the gene expression regulation associated with major psychiatric disorders." (PMID 38219212, 2024). "Fourth, as a cross-sectional study, we cannot suggest if the molecular changes in EGR1 observed were present before illness onset or if these changes are a consequence of the chronic course of the psychiatric disorders." (PMID 38219212, 2024). "In the CNS, c-Fos, Egr1, and Arc are used as a markers of neuronal activity in the context of memory formation and development of multiple psychiatric disorders such as SZ and ASD." (PMID 37234916, 2023). "Our major finding is the downregulation of EGR1 expression in major psychiatric disorders compared to HC when applying a transdiagnostic approach, indicating that EGR1 may be part of a putative pathway underlying a common physiopathology of such illnesses." (PMID 38219212, 2024). "Last, is the EGR1-miR-30a-5p-NEUROD1 axis altered in patients with other psychiatric disorders?" (PMID 28072411, 2017). "Finally, EGR1, a transcription factor involved in cell differentiation and mitogenesis that we identified, has been suggested as a significant regulator of neuronal plasticity and in playing a role in both neurological and psychiatric disorders, as well as neurodegeneration." (PMID 33920138, 2021). "This means that changes in EGR1 and EGR3 expression could potentially influence the activity of several biological pathways involved in the pathophysiology of psychiatric disorders." (PMID 38219212, 2024). "EGR1 is downregulated in psychiatric patients, regardless of diagnosis, and may be a potential common target in major psychiatric disorders." (PMID 38219212, 2024).
bacterial infection (9 papers, 2013 to 2024). "Here, we observed that F. prausnitzii significantly changed the expression of transcription factors in colonic epithelial cells, including IRFs and EGR1 related to viral and bacterial infection." (PMID 39421254, 2024). "In bacterial infections such as Pseudomonas aeruginosa, Porphyromonas gingivalis, and Helicobacter pylori, Egr-1 activation upregulates inflammatory mediators." (PMID 38233877, 2024). "Histopathological examination showed noticeable meningeal thickening and corresponding inflammatory cell accumulation after bacterial infection in WT mice, but this histologic lesion was ameliorated in Egr-1−/− mice." (PMID 38233877, 2024). "EGR1 is commonly induced in host cells during bacterial infection through EGFR-ERK1/2 and integrin signaling pathways, and through VEGF." (PMID 37795301, 2023). "This is somewhat surprising given the availability of EGR1 knockout mice, which have been used to elucidate the importance of EGR1 for other infectious diseases, including bacterial infections." (PMID 36338037, 2022). "We observe enrichment of Egr-1 within all patients in this study, a likely reflection of bacterial infection due to cell adhesion and invasion." (PMID 33753735, 2021). "However, Egr-1 knockout provided protection from mortality in 60% of the Egr-1−/− mice with bacterial infection." (PMID 38233877, 2024). "However, these proteins became inconsecutive, irregularly distributed, or scattered around the WT cells upon bacterial infection, whereas this damage was almost completely prevented in the Egr-1−/− hBMEC." (PMID 38233877, 2024). "Early growth response 1 (Egr-1), also known as NGFI-A, Krox24, Tis8, Zif268, and ZENK, is a zinc-finger transcription factor that is rapidly and transiently induced by a broad range of extracellular stimuli, including bacterial infections, growth factors, cytokines, stresses, and injury." (PMID 35096638, 2021).
kidney diseases (8 papers, 2022 to 2025). "Early growth response factor-1 and -2 (EGR1, EGR2) have been implicated as important pro-fibrotic transcription factors in kidney diseases." (PMID 37752256, 2024). "Egr-1−/− mice exhibit protection against kidney disease through attenuation of renal proximal tubule injury and suppression of NF-κB activity." (PMID 38233877, 2024). "Recent studies indicate Egr-1 contributes to the development of various kidney diseases by promoting renal inflammation and fibrosis." (PMID 35441585, 2022). "As a class of small single-stranded noncoding RNA, miR-34a is involved in the pathological process of various diseases such as dietetic kidney disease by regulating the function of target genes such as Egr1, GAS1, and Sirt1/HIF-1α." (PMID 36345369, 2022).
metabolic disorders (6 papers, 2017 to 2026). "As Egr1-deficient mice exhibit partial protection against fat deposition under HFD conditions, the possibility that EGR1 is a target of metabolic disorders is further strengthened by our findings." (PMID 40141675, 2025). "Severe hypothermia causes metabolic disorders in cerebral cortex nerve cells, significantly altering ferroptosis-related genes such as PPARG, SCD, ADIPOQ, SAT1, EGR1, and HMOX1." (PMID 39125656, 2024).
neurodegenerative disease (5 papers, 2016 to 2025). A disorder of the central nervous system characterized by gradual and progressive loss of neural tissue and neurologic function. "LEF1-associated target genes related to neurodegenerative diseases, such as EGR1, RHOB, and ID2, exhibit binding peaks." (PMID 40918098, 2025). "RNA sequencing analysis showed that BzATP/LPS upregulated 25 genes, including early-growth response protein 1, (Egr1) which increased in the brain of subjects with neurodegenerative diseases." (PMID 38254713, 2024).
neurological diseases (5 papers, 2009 to 2023). "Amongst the substantial TFs associated with the DEGs were early growth response 1 (EGR1), signal transducer and activator of transcription 3 (STAT3) and peroxisome proliferator activated receptor gamma (PPARG), which are involved in different neurological diseases." (PMID 32967368, 2020).
breast (4 papers, 2013 to 2024). "In the second, we explored whether EGR1 or CISD2 expression level would be affected by treatment with hydrogen peroxide in lung ADC cells." (PMID 28928421, 2017).
hematological malignancies (4 papers, 2016 to 2022). "Transcription factors activated in both liver and muscle include Irf8, Jun, Egr1, Cebpa, Foxl2, the hypoxia-inducible factor Hif1a, and Runx1, a key regulator in hematological malignancies." (PMID 35865523, 2022). "The inhibition of Egr1, Hmga1 and Zfp36l2 transcripts was also related to hematological disease by IPA analysis, especially defects in erythropoiesis in CPF and ETU." (PMID 27905518, 2016).
vascular disorder (4 papers, 2012 to 2023). A general term used to describe any disease affecting blood vessels]. "The immediate-early gene Egr-1 controls the inducible expression of many genes implicated in the pathogenesis of a range of vascular disorders, yet our understanding of the mechanisms controlling the rapid expression of this prototypic zinc finger transcription factor is poor." (PMID 22792188, 2012). "In many models of vascular disorders, researchers have shown an increase in the levels of a zinc finger transcription factor called EGR1." (PMID 38275601, 2023). "Histological investigations suggested a potential role for EGR1 in PH-related vasculopathy of the right ventricle." (PMID 35625405, 2022). "Egr-1 is thus key in the pathogenesis of vascular disorders, yet our understanding of the mechanisms controlling its expression is poor." (PMID 22792188, 2012).
brain diseases (2 papers, 2019 to 2024). "Dysregulation of EGR1 expression has been associated with many pathological conditions such as tumors and brain diseases." (PMID 30925677, 2019).
cardiac disease (2 papers, 2015 to 2021). "Given the wide variety of cardiopathologies in which both EGR1 and MEF2 have been implicated, further investigation of EGR1’s function as a potent MEF2 repressor will provide additional insight into mechanisms of various cardiopathologies and into potential targets for treatment of cardiac disease." (PMID 26011708, 2015).
central nervous system diseases (1 paper, 2024). "Many studies have shown that EGR1 is abnormally expressed in various diseases, such as tumors, central nervous system diseases, and cardiovascular and inflammatory diseases." (PMID 38943627, 2024).
connective tissue disease (1 paper, 2020). "EGR1 is a regulator of immune function, and is important in vascular homeostasis, psychological stress, connective tissue disease, mitochondrial function, all of which are relevant to ME/CFS." (PMID 33114612, 2020).
immune disorders (1 paper, 2021). "EGR1 expression trajectory in aged HSC highlighted a signature enriched in hematopoietic and immune disorders with the best induction of AP-1 complex and quiescence regulators such as EGR1, BTG2, JUNB, and NR41A." (PMID 34294125, 2021).
inflammation (1 paper, 2022). Aberrant reaction of the microcirculation characterized by movement of fluid and leukocytes from the blood into extravascular tissues. "A previous study showed that Egr-1 deficiency attenuates renal inflammation in Egr1−/− mice." (PMID 35441585, 2022).
neurodevelopmental disorder (1 paper, 2020). A behavioral and cognitive disorder with onset during the developmental period that involves impaired or aberrant development of intellectual, motor, or social functions. "For an extensive review of established function of EGR-1 in neurodevelopmental disorders and upstream and downstream targets, see Duclot and Kabbaj." (PMID 33050454, 2020).
peripheral neuropathy (1 paper, 2019). A disorder affecting the peripheral nervous system. "In line with this idea, we showed previously in neuropathic rats that the MCS-induced analgesia is accompanied by complete reversion of spinal hyperactivity induced by peripheral neuropathy, which was manifested by a decrease in Egr-1-IR in the spinal cord." (PMID 30909927, 2019).
EGR1 also shares sentences with these, for which no sentence is quoted: acute myocardial infarction (6 papers); bipolar disorder (5); multiple myeloma (5); adenocarcinoma (4); hyperlipidemia (4); mesothelioma (4); thyroid cancer (4); acute lung injury (3); head and neck cancer (3); squamous cell carcinoma (3); Wilms tumor (3); abdominal aortic aneurysm (2); Dyskinesia (2); glaucoma (2); infectious disease (2); kidney (2); pterygium (2); rectal cancer (2); /T-cell lymphoma (1); Achalasia (1); acute respiratory distress syndrome (1); adrenocortical cancer (1); adrenocortical tumors (1); African trypanosomiasis (1); airway hyperresponsiveness (1); anaplastic large cell lymphoma (1); Arrhythmia (1); autoimmune disorders (1); bladder urothelial carcinoma (1); bone cancer (1).
A further 77 diseases each share a sentence with EGR1 in 1 paper.